IL4 (interleukin 4)
Diseases named in the same sentence as IL4 in open-access papers (continued):
Sharing a sentence is not in itself a finding about the gene and the disease.
allergic asthma (continued). "Treatment with melatonin has been shown to reduce levels of a number of cytokines including IL-4 in a murine model of allergic asthma and to reverse ketamine-induced schizophrenia-like behavioral alterations and increments in hippocampal IL-4 in mice." (PMID 29464121, 2017). "Levels of IL-9 and IL-4 in children with allergic asthma(30.23 ± 1.92 pg/ml and 25.81 ± 2.14 pg/ml, respectively) were significantly higher than those in healthy children (67.37 ± 9.27 pg/ml and 49.50 ± 9.99 pg/ml, respectively)." (PMID 28724400, 2017). "Its production is stimulated early in the allergic asthma cascade by the release of IL-4, IL-5, and IL-13 through activated Th2 cells." (PMID 29176991, 2017). "Our results showed that peripheral blood mononuclear cells (PBMCs) from children with allergic asthma produced higher levels of IL-9 and IL-4 and lower levels of IFN-γ than healthy children." (PMID 28724400, 2017). "SerpinB3 and serpinB4 were upregulated in affected skin of eczema patients and in the airway epithelia of patients with allergic asthma, induced via a pathway involving the Th2 cytokines IL-4 and IL-1347–49." (PMID 29051540, 2017). "CpG promoter loci of allergic asthma genes (e.g., interleukin 4 (IL4), interferon gamma (IFNγ), inducible nitric oxide synthase (NOS2A)), arginase 2 (ARG2)) were pyrosequenced at the start and end of each sampling period." (PMID 28588744, 2017). "In the allergic asthma model, the Th2 cytokines, such as IL-4, IL-5, and IL-13, were clearly increased in the lung tissues." (PMID 27669297, 2016). "Itk is recognized as an important component of TCR signalling required for the development of Th2 pathology and expression of IL-4 in response to parasites and allergic asthma models." (PMID 26936133, 2016). "In this study, we investigated a commercially sourced, procyanidin A2 for in vitro efficacy in modulating interleukin-4 (IL-4)-induced CCL26 production relevant to allergic asthma." (PMID 27845745, 2016). "Allergic asthma is another prototypical Th2 cytokine-driven disease which strongly instructs E-cadherin expression in M(IL-4/IL-13) macrophages." (PMID 26226941, 2015). "Allergic asthma is considered to be a Th2 disease and is thus accompanied by IL-4/13-polarized M2 alveolar macrophages in the airways." (PMID 26635789, 2015). "Altogether, these results suggest that the IL-4-producing Tfh cells are involved in the pathogenicity of allergic asthma and Batf is important in controlling the IL-4 level in these cells." (PMID 26278622, 2015). "In typical Th2-type allergic asthma, interleukin (IL)-4 and IL-13 predominate, driving IgE production and recruitment of eosinophils into the lungs." (PMID 26635789, 2015). "IL-4 and IL-13 are two such cytokines that have been shown to play a central role in directing the pathophysiological changes in allergic asthma." (PMID 26362930, 2015). "In the present study we used a sheep model of allergic asthma to investigate the kinetics of expression of IL-4 and IL-13 in allergen-challenged airways, with the goal to extend our understanding of Th2-driven mechanisms in this large animal model system." (PMID 26362930, 2015). "IL-2 and IL-4 producing cells showed a significant decrease (P = 0.018 and P = 0.001, but in a steady fashion for IL-4), confirming the murine data about the potential beneficial effects of aerobic exercise for allergic asthma." (PMID 25050349, 2014). "Th2 cells are critical for the induction of allergic asthma via production of IL-4, IL-5, IL-13, and eotaxin." (PMID 24658532, 2014). "Th2 cytokines including IL-4, IL-5, and IL-13 have been shown to play crucial roles in the regulation of pulmonary inflammatory responses in allergic asthma." (PMID 25415454, 2014). "Taken together, our results demonstrate possible therapeutic potentials of sesamin in reducing the TH2 immune reaction sand the following inflammatory response mediated by IL-4, IL-5, and IL-13 in human allergic asthma." (PMID 24755955, 2014).
allergic asthma (continued). "It is known that, among the several cytokines involved in the allergic asthma pathogenesis, IL-4 plays a fundamental role." (PMID 25050349, 2014). "Imbalance in TH17/Tregs, elevated IL-17, and IL-4 response and downregulation of FOXP3 were associated with allergic asthma." (PMID 24995020, 2014). "Allergic asthma is primarily mediated by Th2 cells, which secrete the characteristic cytokines IL-4, IL-5, and IL-13." (PMID 24955743, 2014). "Th2 cell, a sub-group of lymphocytes, plays an important role in the initiation and progression of allergic asthma by releasing of IL-4 and IL-5 cytokines." (PMID 23837463, 2013). "It is well known that overexpression of GATA-3 predisposes for Th2-mediated diseases such as allergic asthma and suppression of GATA-3 expression in the lung reduces IL-4, IL-5, and IL-13 productions concurrently." (PMID 23800145, 2013). "T helper 2 (Th2) cytokines, including IL-4, IL-5 and IL-13, predominate primarily in mild to moderate allergic asthma." (PMID 24204835, 2013). "IL-4 and IL-13 are key Th2 cytokines that direct many of the important features of airway inflammation and remodeling in patients with allergic asthma." (PMID 24204835, 2013). "IL-4 is also known to suppress TH17 development in a STAT-6 dependent manner with IL-4Rα−/− mice producing increased levels of IL-17 in an allergic asthma model." (PMID 23284939, 2012). "While IL-4 and IL-5 are known to be upregulated in allergic asthma, IFN-γ is generally thought to be downregulated." (PMID 21810230, 2011). "In a mouse model of allergic asthma, administration of anti-B7-H3 mAbs significantly reduced airway hyperactivity and resulted in decreased production of Th2 cytokines (interleukin-4 (IL-4), IL-5, and IL-13) as compared with control IgG-treated mice." (PMID 21127709, 2010). "The combination of IL-4Rα (148 G/A: Val50Ile) and IL-4 (-590 C/T) was also associated with CAA (P = 0.00689); association between allergic asthma and this combination has previously been reported." (PMID 15339344, 2004). "In an allergic asthma model, BATF-deficient mice exhibited reduced symptoms of asthma, including a decrease in eosinophils and lymphocytes, and a significant reduction in cytokines such as IL-4, IL-5, and IL-13 in the lungs." (PMID 39876010, 2025). "A study performed in a murine model of HDM allergic asthma revealed that both 2’FL and 6’SL at biologically relevant doses decreased the amount of circulating IgE, decreased levels of IL4 and IL6 in the lungs, and decreased inflammatory cell infiltration in the lungs." (PMID 40636105, 2025). "Firstly, this study observed that the activity of peripheral blood Th1 cytokines (such as IL-2, IFN-γ) was significantly reduced, while the activity of Th2 cytokines (such as IL-4, IL-13) was significantly enhanced in children with acute exacerbations of allergic asthma." (PMID 40260311, 2025). "Allergic asthma is generally classified as an eosinophilic airway disorder, and previous studies have focused on the role of Th2 cells and type 2 cytokines, including IL-4, IL-5, and IL-13." (PMID 38790633, 2024). "OVA-induced allergic asthma increased the levels of Inf-γ (Th1 cytokine), Il-4 and Il-13 (Th2 cytokines), and Il-17a (Th17 cytokine) mRNAs in BALF cells, whereas the administration of empagliflozin or canagliflozin administration reduced the extent of these increases." (PMID 39062810, 2024). "In recent years, several biologic antibodies have been clinically introduced such as omalizumab (anti-IgE), dupilumab (anti-IL-4), and mepolizumab (anti-IL-5), because IgE and Th2 cytokines (IL-4, IL-5, and IL-13) play crucial roles in allergic asthma pathogenesis." (PMID 39062810, 2024). "Elevated gene expression levels of IL-4 and IL-13, detected in our study, might explain the development of long-term allergic asthma often observed in humans after prolonged exposure to welding fumes or ZnO inhalation." (PMID 38097754, 2023).
allergic asthma (continued). "The increased levels of IL-4 and IL-13 cytokines may explain the development of long-term allergic asthma after exposure to ZnO nanoparticles, which is well-known among welders, smelters, and metal workers." (PMID 38097754, 2023). "made similar observations and demonstrated that variations in gut microbiota composition could effectively differentiate patients diagnosed with allergic asthma (IL-4 high) from non-allergic asthma (IL-4 low) patients." (PMID 38274730, 2023). "The data from our study exhibited that naringenin can effectively improve allergic asthma by reducing the levels of IL-4 and IL-13 in the lung tissue and reducing the count of eosinophils in BALF, which indicates the anti-inflammatory properties of this phytochemical on the pulmonary system." (PMID 35419072, 2022). "In a mouse model of allergic asthma, SGK1 deficiency significantly reduces Th2 cell differentiation, while bronchoalveolar lavage fluid from Sgk1 gene knockout mice has lower concentrations of IL-4 and IgE, and mice were, therefore, resistant to Th2 cell-mediated allergic asthma." (PMID 35222400, 2022). "In addition, a previous study proved that elevated level of interleukin-4 (IL-4) and interleukin-17 (IL-17) and decreased level of interferon-γ (IFN-γ) were associated with pathogenesis of allergic asthma." (PMID 35356750, 2022). "Previous studies provide evidence that AD and allergic asthma might share related drivers -i.e., IL-4 and IL-13- and that both conditions may benefit from a common therapeutic inhibition of these Th2 cytokines with dupilumab." (PMID 36035412, 2022). "Subsequent work in the same group found that upper-airway IL-24, an IL-4-induced epithelial type 2 cytokine, could be used as a proxy for lower-airway IL-24 to diagnose allergic asthma." (PMID 36032162, 2022). "ClusterB was highly linked to the Th2 immune response and had higher expression levels of TSLP, IL-33, IL-4, IL-5, and IL-13, which indicated that clusterB may be related to allergic asthma." (PMID 33763115, 2021). "Furthermore, because allergic asthma is considered a Th2‐type disease, Th2 cytokines such as IL‐4 and IL‐13 are widely applied in vitro to mimic the asthmatic environment." (PMID 33960626, 2021). "In addition, P. cocos extract markedly suppressed Th2cytokines, IL-4, IL-5, and IL-10, secretions that have been suggested as a potential therapeutic target in allergic asthma." (PMID 33919400, 2021). "IL-4 and IL-13 cause M2 macrophages to express TGF-β, which, in turn, induces the proliferation of airway smooth muscle cells, fibrosis, and airway remodeling in allergic asthma." (PMID 33919784, 2021). "In addition to IL-4, IL-13 also contributes in the progression of allergic asthma by promoting mucus hypersecretion and eosinophils accumulation." (PMID 32617136, 2020). "Anti-inflammatory effects of quercetin such as reduction of IL-4 and IgE in serum could be useful on allergic asthma." (PMID 32467711, 2020). "In summary, this study demonstrated that RHAS could improve systemic immune response by elevating the Th1/Th2 cell ratio and decreasing the levels of IgE and IL-4, thereby effectively preventing the recurrence of allergic asthma." (PMID 32509851, 2020). "To explore how TLR2 agonist and miR146a-mimic attenuate OVA-induced allergic asthma, we considered Th1 cytokines, including IgE, IL-4, IL-5 and IL-13, might be involved." (PMID 32600285, 2020). "In addition, we tried to shed light on the relationship between NFATc1 and NFATc2 and IRF4, another transcription factor upregulating cytokines like IL‐4 and IL‐9 involved in allergic asthma." (PMID 33079489, 2020). "Therefore, the higher secretion of IL-4, IL-5, and IL-13 contributes substantially to inflammation in allergic asthma." (PMID 32617136, 2020). "The pathogenesis of allergic asthma involves Th2-type cytokines, such as IL-4, IL-5, and IL-13." (PMID 32915886, 2020).
allergic asthma (continued). "IL-4 plays several important roles in the pathogenesis of allergic asthma and allergic rhinitis." (PMID 32256362, 2020). "IL-4 and IL-13 are crucial to the development of TH2 cells and induction of IgE isotype switching from B cells, which are the major risk factor for the development of allergic asthma." (PMID 31275149, 2019). "Thus, our data suggest that NIP45 not only plays a crucial role in the differentiation of Th2 cells but also in the differentiation of ILC2s in allergic asthma, because it is able to induce IL-4 as well as IL-13." (PMID 31666531, 2019). "Both IL-4 and IL-9 are known to shape the immune response in allergic asthma." (PMID 31703379, 2019). "The Th2 cytokines, IL-4, IL-5, and IL-13, were increased in patients of allergic asthma." (PMID 29086354, 2018). "In addition, α-GalCer injection promotes a significant increase in OVA-specific Th2 polarization in an iNKT cell-dependent manner, suggesting that iNKT cell-derived IL4 contributes to the induction of allergic asthma." (PMID 29973666, 2018). "Interestingly, a recent study in a mouse model reported that allergic asthma also decreases lung infection with Klebsiella pneumoniae in a neutrophil-dependent and IL-4- and IL-17-independent manner." (PMID 30147700, 2018). "The IL-4 gene was shown to be hypomethylated in a mouse model of childhood allergic asthma." (PMID 28969068, 2017). "In addition, it has been reported that the administration of 5 mg/mL of hesperidin in a mouse model of allergic asthma inhibited the IL-4 production in splenocytes and the IL-5 concentration in the bronchoalveolar fluid." (PMID 28587283, 2017). "The characteristic features of allergic asthma, including airway hyperreactivity, histopathology, cytokines (IL-4, IL-5, IL-13, IL-17, and INF-γ), and CD4+CD25+Foxp3+Treg cells in bronchoalveolar lavage fluid (BALF), and downstream proteins of mTORC1/2 signaling were examined." (PMID 29234390, 2017). "Th2 cells and IL-4-driven M2 polarization play active roles in the pathogenesis of allergic asthma." (PMID 28620389, 2017). "For example, in the pathogenesis of allergic asthma, IL-4 and IL-13 play an important role in tandem, with IL-4 having a pivotal role in Th2 cell proliferation, cytokine production and IgE synthesis, whilst IL-13 plays a pivotal role in the effector phase of the disease." (PMID 26870894, 2016). "IL-4 is one of the key players in the development of allergic asthma." (PMID 26003185, 2016). "IL-4 and IL-13 play a critical yet poorly understood role in orchestrating the recruitment and activation of effector cells of the asthmatic response and driving the pathophysiology of allergic asthma." (PMID 26362930, 2015). "Doing so in vivo, macrophage E-cadherin could help to determine the outcome of typical Th2 cytokine-driven diseases like Taenia crassiceps helminth infection and allergic asthma, during which E-cadherin-expressing M(IL-4/IL-13) macrophages are present." (PMID 26226941, 2015). "Allergic asthma is characterized by overproduction of IL-4, IL-13 and high level of serum IgE." (PMID 24681543, 2014). "Moreover, Th2 cytokines such as IL-4, Il-5 and IL-13 are crucial for the pathogenesis of allergic asthma." (PMID 24671176, 2014). "There is overwhelming evidence linking IL-4 and IL-13 signaling to allergic asthma responses." (PMID 23940740, 2013). "However, several reports have shown increased production of IFN-γ in addition to IL-4 and IL-5 in allergic asthma." (PMID 21810230, 2011). "IL-4, together with IL-13, is required for Th2-cell development and is intimately involved in the regulation of immunoglobulin E (IgE) production by sensitized allergen-specific B cells, which is a fundamental mechanism in the pathogenesis of allergic asthma." (PMID 20671916, 2010). "In addition, both IL-4 and IL-13 genes have been reported to be increased 18 h after allergen exposure in patients with allergic asthma." (PMID 16551361, 2006).
allergic asthma (continued). "Allergic asthma is related to type I hypersensitivity reactions in which different allergens, such as pollen, and dust mites, induce type 2 immune responses, which are defined by the generation of interleukin-4 (IL-4), IL-5, and IL-13 and class switching to IgE antibodies." (PMID 40375219, 2025). "For instance, in an allergic asthma model due to exposure to house dust mites or in another one, with a mouse infected with Heligmosomoides polygyrus, miRNA-15a-5p, miRNA-20b-5p, miRNA146a-5p, miRNA-155-5p and miRNA-200c-3p successfully differentiate Th2 cells (IL-4+) profile." (PMID 41294623, 2025). "Additionally, IL-4 enhances the polarization of naive T cells into Th2 cells, thereby amplifying the overall Th2-driven inflammatory response, which is characteristic of allergic asthma." (PMID 39664985, 2024). "Additionally, in an in vivo study of ovalbumin-instigated allergic asthma, eugenol reduced ovalbumin-specific IgE levels, as well as interleukin-4 and -5 (IL-4 and-5), the primary cytokines in various types ofallergic reactions, preventing the emergence of a Th2-type immune response." (PMID 36770859, 2023). "Considering that the airway inflammatory microenvironment is rich in Th2 cytokines such as IL-4 and IL-13, which are the primary inducers of M2 macrophage polarization, it is currently thought that M2 macrophages play major pathological roles in allergic asthma." (PMID 34456917, 2021). "Our results imply that dual IL-4/IL-13 vaccination may represent a cost-effective, long-term therapeutic strategy for the treatment of allergic asthma as demonstrated in mouse models, although additional studies are warranted to assess its safety and feasibility." (PMID 33976140, 2021). "On the other hand, it is noteworthy that published evidence clearly supports the proposition that overproduction of IL-4 and IL-13 may be responsible for the features of allergic asthma that are exacerbated in the offspring born to HFD-fed mice after challenge with OVA." (PMID 31805682, 2019). "In addition to enhanced IFN-γ/IL-4 ratio, Z. multiflora hydro-ethanolic extract also caused potentiation of TH1 and suppression effect on TH2 and TH17 cells, which led to therapeutic effect on allergic asthma in ovalbumin-sensitized BALB/c mice." (PMID 31275149, 2019). "One explanation is that IL-31 is one of these Th2-type cytokines that induce inflammation-related cytokines, such as IL-4, IL-5 and IL-13, which form the complex network of cytokines that governs the development allergic asthma and so that role of IL-31 may be covered by other stronger cytokines." (PMID 30647024, 2019). "Furthermore, NK-4 abrogated the IL-4-driven alteration of cytokine expression profile in THP-1 cells, suggesting a regulatory effect of NK-4 on IL-4-mediated signaling events that are involved in polarization to AAM phenotype, which is proposed to have pathogenic roles in allergic asthma." (PMID 29933387, 2018). "In addition, in allergic inflammatory diseases such as allergic asthma, where the levels of IL4 are elevated, it is possible that this could drive the presence of nTh1 cells." (PMID 28406139, 2017). "While IL-4 and IL-5 promote isotype switching of B cells to IgE producing cells and the infiltration of target tissues by eosinophils, IL-13 induces metaplasia of epithelial cells into goblet cells which is responsible for mucus hypersecretion in allergic asthma." (PMID 26999446, 2016). "Eosinophils and mast cells may also be a source of IL-4 and IL-13, and in this study and earlier investigations these cells have been shown to be a key feature of the inflammation seen in the sheep model of allergic asthma." (PMID 26362930, 2015). "Therefore, we speculated that FA may have an antiallergic effect on allergic asthma by suppressing IL-4 secretion which consequently reduces IgE production and eosinophil infiltration into the lungs." (PMID 26495021, 2015).